MMP9 (matrix metallopeptidase 9)
Diseases named in the same sentence as MMP9 in open-access papers (continued):
Sharing a sentence is not in itself a finding about the gene and the disease.
bronchiolitis obliterans (3 papers, 2008 to 2025). "MMP-9 deficient mice were also shown to be protected from obliterative bronchiolitis as evidenced by reduced neutrophil influx and collagen deposition." (PMID 26264019, 2015). "Taghavi and coworkers have described increased MMP-9 and MMP-8 levels in bronchiolitis obliterans from lung transplant patients." (PMID 18700005, 2008). "Furthermore, proteolytic enzymes commonly associated with extracellular matrix degradation and neutrophil migration, including metalloproteinases (such as MMP9 and MMP8), have been identified at elevated levels in patients affected by bronchiolitis obliterans syndrome (BOS), a form of CLAD." (PMID 40283490, 2025).
carcinoma in situ (3 papers, 2012 to 2022). "Microarray analysis of BC profiles (GDS1479) in GEO confirmed that MMP2 and MMP9 mRNA level in MIBC tissues was remarkably increased compared with that in carcinoma in situ tissues." (PMID 35449123, 2022). "MMP2 and MMP9 were highly expressed in the MIBC tissue compared with carcinoma in situ tissue, suggesting that MMP2 and MMP9 are diagnostic markers for detecting MIBC." (PMID 35449123, 2022).
cerebral small vessel disease (3 papers, 2023 to 2024). Cerebral small vessel disease is the term currently used to pathological processes that affect the brain parenchymal circulation (arterioles, capillaries, and veins). "Herein, we aimed to investigate the relationship between changes in serum YKL-40 and MMP-9 levels and positive intracranial arterial remodelling in patients with cerebral small vessel disease (CSVD)." (PMID 37091521, 2023). "Melatonin could inhibit MMP‐9 secretion from pericytes via inactivating NOTCH3/NFκB pathway, further protect BBB integrity against pericyte‐derived MMP‐9 in cerebral small vessel disease." (PMID 39548663, 2024).
chlamydial infection (3 papers, 2006 to 2017). "There is evidence to suggest that the elevated local levels of TNF and IL-1β associated with chlamydial infection and inflammation act as an important trigger of matrix degradation by inducing MMP-9 activity in inflamed tissue." (PMID 16643654, 2006). "Further studies of MMP-9 in chlamydial infection and of the functional significance of genetic variation at the MMP-9 locus, are warranted." (PMID 16643654, 2006).
cholestasis (3 papers, 2014 to 2025). Impairment of the bile flow caused by obstruction within the liver, or outside the liver in the bile duct system. "In patients with malignant hilar biliary obstruction treated by external percutaneous biliary drainage for cholestasis resolution, a significant reduction in MMP-9 serum values was noted 4 weeks after the treatment." (PMID 36837539, 2023). "In patients with malignant hilar biliary obstruction treated by external percutaneous biliary drainage for cholestasis resolution, a significant reduction in MMP-9 serum values was noted." (PMID 36837539, 2023). "During this study, we investigated changes in MMP-9 activity before and after percutaneous biliary drainage performed for cholestasis treatment in order to achieve liver regeneration." (PMID 36837539, 2023). "Based on a previously established role of MMP-9 in liver regeneration, we hypothesized that the enzymatic activity of MMP-9 is in correlation with cholestasis resolution after percutaneous biliary drainage." (PMID 36837539, 2023). "In conclusion, after cholestasis an increase in hepatic ADMA in RL and ML was detected as well as tissue MMP-2 and MMP-9 activation in RL, supporting the evidence of functional heterogeneity among the liver lobes also occurring in an obstructive cholestasis model." (PMID 25013773, 2014).
CNS leukemia (3 papers, 2011 to 2020). "MMP9, secreted by leukemic cells, mediates opening of the blood–brain barrier by disrupting tight junction proteins in CNS leukemia." (PMID 33109189, 2020).
co-infection (3 papers, 2014 to 2025). "A study on HIV-HCV co-infection revealed that ribavirin and interferon can alter MMP9 abundance in vitro and in vivo, highlighting the potential influence of drug-gene interactions in MMP9 regulation." (PMID 40574839, 2025). "In disagreement with our study, serum MMP-2 and MMP-9 and TIMPs in HCV patients were reported either similar to control levels or increased, particularly in those with HCV/HIV co-infection and chronic HBV." (PMID 36551935, 2022). "Importantly, co-infection with AdSIRT1 largely abolished the promoting effects of IRF9 on Cyclin D1 and MMP9 promoter activities." (PMID 25319116, 2014).
conjunctivitis (3 papers, 2021 to 2024). Inflammation of the conjunctiva of the eye. "In particular, MMP-2 and MMP-9 cause the disruption of corneal barrier with the digestion of mucins, resulting in an increase in corneal irregularity and permeability and conjunctivitis with the desquamation of the corneal epithelium." (PMID 38885258, 2024). "In return, seasonal conjunctivitis differs from perennial conjunctivitis with regard to higher concentrations of IgA and MMP-9." (PMID 35935953, 2022). "Moreover conjunctivitis has shown a rise in inflammatory mediators (IL-1β, TNF-α, and MMP-9) and the activation of proinflammatory mitogen-activated protein kinase (MAP-K) pathways." (PMID 34615949, 2021).
cor pulmonale (3 papers, 2016 to 2023). Hypertrophy and dilation of the right ventricle of the heart that is caused by pulmonary hypertension. "Thus, we speculate that baicalin attenuates pulmonary arteriole remodeling and hypoxic pulmonary hypertension, further improving cor pulmonale by inhibiting the activity of p38 MAPK and downregulating the expression of MMP-9 in arterioles." (PMID 27688788, 2016).
corneal disease (3 papers, 2012 to 2019). "Our results show for the first time the significant differences in the levels of MMP-9 in tear samples between these two ectatic corneal disorders." (PMID 27074131, 2016). "This strategy may be clinically helpful for the treatment of corneal diseases in which MMP-9 activity and inflammatory cytokines are upregulated." (PMID 31003493, 2019). "Further, in support of the contribution of IL-17A in the corneal disease that develops in the nude recipients, we measured the number of IL-17A, CCL20, MMP-3 and MMP-9 mRNA transcripts in this tissue." (PMID 22590618, 2012).
cutaneous squamous cell carcinoma (3 papers, 2021 to 2025). "Additionally, research has demonstrated that tumor-associated neutrophil-derived MMP9 contributes to tumor angiogenesis and progression associated with cutaneous squamous cell carcinoma." (PMID 37507767, 2023).
dacryoadenitis (3 papers, 2016 to 2022). Inflammation and enlargement of the lacrimal gland. "In the current study, we found that ADSC treatment significantly downregulated the mRNA expression of MMP-2 and MMP-9 in the LGs of dacryoadenitis rabbits." (PMID 27699412, 2016). "Decreased production of MMP-2 and MMP-9 could lead to reduced leukocyte recruitment to the LGs, resulting in diminished inflammatory infiltrates in the LGs of dacryoadenitis rabbits treated with ADSCs." (PMID 27699412, 2016).
dermatomyositis (3 papers, 2016 to 2026). Dermatomyositis (DM) is a type of idiopathic inflammatory myopathy characterized by evocative skin lesions and symmetrical proximal muscle weakness. "Network toxicology analysis suggested that BPA may influence the progression of dermatomyositis by regulating key factors such as AKT1, BCL2, MMP9, ESR1, and INS, thereby affecting apoptosis, immune-inflammatory responses, pathways in cancer, and the PI3K-Akt signaling pathway." (PMID 41911226, 2026).
endometrial adenocarcinoma (3 papers, 2022 to 2025). "Compared with common endometrial adenocarcinoma cells, the high migration capability of PDTCs may result from the up-regulated mRNA expression of MMP9." (PMID 40231208, 2025). "An in vitro study of the anti-tumor activity of curcumin in endometrial adenocarcinoma found that curcumin suppressed cancer cell migration, accompanied by a significant reduction in MMP-2 and MMP-9 protein expression." (PMID 39335164, 2024).
enteropathy (3 papers, 2016 to 2023). "Because the present study regimen caused intestinal toxicity, we investigated the possibility that the extent of decline in serum LCN2 and MMP9 levels might also, in susceptible individuals, predict treatment-induced enteropathy, clinically presenting as diarrhea." (PMID 27461255, 2016).
Erythema (3 papers, 2020 to 2025). Redness of the skin, caused by hyperemia of the capillaries in the lower layers of the skin. "MMP‐9 levels were much higher in patients with erythema, showing this group a slight increase throughout the treatment." (PMID 31568637, 2020). "Our results suggest that MMP‐9 and TIMP‐3 levels could be predictive of RT toxicity, particularly, of acute effects such as erythema and radiodermitis." (PMID 31568637, 2020).
fluorosis (3 papers, 2024). "The Col1a1, Bcl2, Fgfr1, Mmp9, Mmp13, Bmp2, and Bmp7 genes are the key regulatory factors in fluorosis bone metabolism." (PMID 39125380, 2024). "The urine fluoride levels, BALP, MMP-2, and MMP9 of the children in the fluorosis group were higher than fluoride-free group, and the mother's educational level, per capita annual household income, OC, and PTH were lower than fluoride-free group (P<0.05)." (PMID 39876909, 2024). "After adjusting for confounding factors, including urinary fluoride, maternal education level, and per capita annual household income, multivariate Logistic regression analysis showed that BALP, OC, MMP-2, MMP-9, and PTH were independently associated with the risk of dental fluorosis (P<0.05)." (PMID 39876909, 2024). "The aim of this study was to investigate the association between dental fluorosis occurrence in children and bone metabolism-related indicators, including bone-specific alkaline phosphatase (BALP), osteocalcin (OC), matrix metalloproteinase (MMP-2, MMP-9, MMP-20), and parathyroid hormone (PTH)." (PMID 39876909, 2024). "High BALP, MMP-2, MMP-9, low OC, and PTH are independent factors affecting the occurrence of dental fluorosis and are related to the extent of dental fluorosis." (PMID 39876909, 2024). "Based on Spearman correlation analysis, a positive correlation was identified between the urinary fluoride level, the extent of dental fluorosis, and indicators such as BALP, MMP-2, and MMP-9." (PMID 39876909, 2024). "As the urinary fluoride level and the extent of dental fluorosis increased, there was a gradual elevation in serum BALP, MMP-2, and MMP-9 levels in children, while OC and PTH levels gradually decreased (P<0.05)." (PMID 39876909, 2024). "In summary, high BALP, MMP-2, MMP-9, and low OC, PTH are independent factors affecting the occurrence of dental fluorosis and are related to the urinary fluoride level and the extent of dental fluorosis." (PMID 39876909, 2024).
follicular thyroid cancer (3 papers, 2018 to 2020). "The production of MMPs has been monitored preclinically, with a probe cleaved by MMP-2 and MMP-9 giving an increase in PAI signal upon cleavage in preclinical models of follicular thyroid carcinoma, which express high levels of MMP-2, MMP-7 and MMP-9 compared to benign thyroid adenomas." (PMID 31337635, 2019). "Interestingly, S1P promotes migration and invasion in human follicular thyroid cancer ML-1 cells and increases the secretion and activity of MMP2 and MMP9 through S1P1,3." (PMID 29734379, 2018).
gastric diseases (3 papers, 2016 to 2024). "Initially, H. pylori was shown to activate MMP-9 expression in gastric epithelial cells, contributing to the development of H. pylori-related gastric diseases." (PMID 39712025, 2024). "To explore the correlation between PGC and other positive tumor markers in different gastric diseases, we observed the expression of PGC, MG7‐Ag, MMP9, NM23, Ki‐67, and E‐cadherin by immunohistochemistry, quantitative RT‐PCR, and immunoblot analysis." (PMID 29963765, 2018). "The expression of a series of molecules related to differentiation (MG7‐Ag), migration (MMP9, NM23), cell proliferation (Ki‐67), and epithelial mesenchymal transition (E‐Cadherin) were observed in different gastric diseases." (PMID 29963765, 2018). "In the present study, we determined the expression of 6 biomarkers in different gastric diseases, including differentiation (PGC, MG7‐Ag), migration (MMP9 and NM23), proliferation (Ki‐67), and epithelial mesenchymal transition‐related protein (E‐Cadherin)." (PMID 29963765, 2018). "Interestingly, though proteins such as Glyoxalase I (GLO1, DD = 3), Nitric Oxide Synthase (NOS1, DD = 3), Matrix metalloproteinase-9 (MMP9, DD = 2) and Acetylcholinesterase (ACHE, DD = 2) do not have high topological properties, they are all the therapeutic targets of stomach diseases." (PMID 27597117, 2016).
gastrointestinal stromal tumor (3 papers, 2017 to 2023). "MMP-9 expression, along with COX-2 and VEGF, were also increased in gastrointestinal stromal tumors (GIST), the most common mesenchymal neoplasms of the gastrointestinal tract." (PMID 32046329, 2020).
giant cell arteritis (3 papers, 2024). "In the context of giant cell arteritis, MMP-9 is the main effector for the loss of immune privilege in the arterial wall, a crucial event in disease initiation." (PMID 38734017, 2024). "The latest research has revealed that in immunodeficient states, monocytes can produce MMP-9, mediating the infiltration of T cells into the vessel wall, leading to giant cell arteritis." (PMID 39253091, 2024). "Giant cell arteritis (GCA) is the most common inflammatory disease of medium and large arteries, and the CD206+MMP-9+ macrophage subset mediates tissue destruction and neovascularization through the Chi3l1/IL-13Rα2 axis in this disease." (PMID 39769202, 2024).
gram-negative bacterial infections (3 papers, 2015 to 2023). Infections caused by bacteria that show up as pink (negative) when treated by the gram-staining method. "MMP9, for example processes epidermal growth factor (EGF) precursors into active EGF receptor ligands thereby co-amplifying inflammation in Gram negative bacterial infection." (PMID 25615645, 2015).
hepatitis C (3 papers, 2019 to 2023). "However, D’Amico and colleagues have previously shown significantly higher MMP-9 plasma levels in NASH patients compared to hepatitis C-infected patients with liver disease." (PMID 31874999, 2019). "The present study shows a decrease in MMP-9 with more advanced fibrosis, these findings are consistent with a previous study that revealed lower concentrations of MMP-9 in hepatitis C patients with advanced fibrosis." (PMID 34813621, 2021).
infectious colitis (3 papers, 2012 to 2024). A viral or bacterial infectious process affecting the large intestine. "Our data suggest that this crosstalk between Lcn2 and MMP-9 in the inflamed gut, which results in increased MMP-9 activity, was crucial for the deleterious impact on the intestinal mucosa observed during infectious colitis." (PMID 24465207, 2014). "Interestingly, using Lcn2 mutant mice we show that lack of Lcn2 effectively reduced tissue damage and the degree of inflammation, thus supporting a pivotal role of Lcn2 and MMP-9 in infectious colitis." (PMID 24465207, 2014). "Taken together, these data show that bioactive MMP-9 is not expressednormally in mouse colon, but protease expression is upregulated in response toan infectious colitis." (PMID 22694805, 2012).
Intestinal tumors (3 papers, 2003 to 2026). "Intestinal tumors in myeloid Mir34a-deficient mice showed elevated expression of several known Mir34a target mRNAs, including Csf1r, Pd-l1, Mmp9, Ccl22, and c-Myc." (PMID 42140945, 2026). "A number of different MMPs may be important in intestinal tumour formation as human tumours have been shown to express interstitial collagenase (MMP-1), gelatinase A (MMP-2), stromelysin 1 (MMP-3), matrilysin (MMP-7), gelatinase B (MMP-9), and stromelysin 3 (MMP-11)." (PMID 12778076, 2003).
ischemic cardiomyopathy (3 papers, 2021 to 2023). Ischemic cardiomyopathy is a cardiomyopathy in which a weakness in the muscle of the heart due to inadequate oxygen delivery to the myocardium with coronary artery disease being the most common cause. "MMP-9, a matrix metalloproteinase involved in degrading the ECM, plays a prominent role in cardiac remodeling after ischemic injury, and is also upregulated during ischemic cardiomyopathy." (PMID 36982525, 2023).
joint diseases (3 papers, 2009 to 2020). "Elevated MMP-2 and MMP-9 activities have been detected in synovial fluid from various joint diseases in man, but in the equine, few data on synovial gelatinase activities are recorded." (PMID 32111016, 2020). "The lack of effect on MMP-2 is not surprising and is consistent with the literature indicating the greater significance of MMP-9 in joint diseases than MMP-2." (PMID 19664212, 2009).
leukoaraiosis (3 papers, 2017 to 2021). "These relationships, and those between MMP-9 levels and blood-brain barrier dysfunction, and between blood-brain barrier permeability and the development of leukoaraiosis, indicate an association between the chronic atheroinflammation within carotid plaques and the development of leukoaraiosis." (PMID 34531813, 2021). "MMP-9 is implicated in blood-brain barrier dysfunction, where increased permeability may promote the development of leukoaraiosis." (PMID 34531813, 2021).
limb ischemia (3 papers, 2016 to 2020). A ischemia that involves the limb. "On day 7 after limb ischemia, the MMP-9 level was significantly higher in the HG group than that in the HC and HI groups." (PMID 32104148, 2020). "Of importance, MMP-9 is expressed in several types of cells involved in limb ischemia and followed recovery, including muscle cells, fibroblasts, endothelial cells, and bone marrow cells." (PMID 27610138, 2016). "The results of our study showed increased plasma inflammatory cytokines and MMP-9 levels as well as upregulated muscle HIF-1α and MMP-9 expressions shortly after limb ischemia." (PMID 32104148, 2020).
liposarcoma (3 papers, 2013 to 2017). A usually painless malignant tumor that arises from adipose tissue. "Furthermore, cells in our 3D model showed an induction of specific biomarkers associated with liposarcoma pathogenesis, e.g. β-catenin and E-cadherin, and aggressiveness, e.g. ALDH1, MMP2, MMP9 and Slug." (PMID 27895047, 2017). "In liposarcoma cells, TNF-α strongly stimulated MMP-9 and showed slight up and down activity on MMP-2." (PMID 24085323, 2013).
lumbar disc degeneration (3 papers, 2012 to 2023). "A polymorphism in the promoter of MMP-1, MMP-2, MMP-3, and MMP-9 genes, which enhance promoter activity, is associated with a higher prevalence of lumbar disc degeneration in Japanese elderly patients and Chinese adult cohorts." (PMID 22394620, 2012). "Other studies on MMP-9 expression have been performed in patients with lumbar disc degeneration, and it was shown that in the group with more advanced vertebral lesions, MMP-9 expression was higher than in patients with milder forms of the disease." (PMID 38138968, 2023).
Mast Cell Tumours (3 papers, 2013 to 2023). "The results obtained in studies on mast cell tumors show that in this case MMP-9 has greater diagnostic and prognostic significance, while the activity of MMP-2 varied depending on the degree of tumor differentiation, but not to such a significant extent." (PMID 37895400, 2023). "We also observed the same results in canine mast cell tumours, in which the release of VEGF by mast cells is correlated with higher MMP-9 production." (PMID 23641796, 2013).
monocytic leukemia (3 papers, 2011 to 2016). "It has been previously reported that IL-1β induces both TIMP-1 and MMP-9 in monocytes and monocytic leukemia cells." (PMID 23967215, 2013).